TACSTD2 (tumor associated calcium signal transducer 2)
Diseases named in the same sentence as TACSTD2 in open-access papers (continued):
Sharing a sentence is not in itself a finding about the gene and the disease.
adenocarcinoma (32 papers, 2012 to 2026). A common cancer characterized by the presence of malignant glandular cells. "In PRAD, genes and pathways enriched at the sites of TEAD peaks include actin filament organization, epithelial morphogenesis, and cell substrate adhesion, all consistent with an adenocarcinoma lineage (exemplified by Tacstd2)." (PMID 41509338, 2025). "Further sub-classification of patients with adenocarcinoma into luminal or basal subtypes revealed that tumors from these patients had markedly elevated TACSTD2 expression compared to tumors from patients with NEPC." (PMID 38794221, 2024).
infection (3 papers, 2018 to 2022). The state of being infected such as from the introduction of a foreign agent such as serum, vaccine, antigenic substance or organism. "Other transcription factors associated with lung injury/infection and anti-viral response that has been previously identified as TACSTD2 regulators include CREB and p538,71,73–76." (PMID 35688908, 2022). "Third, Tacstd2 upregulation in the lungs after an infection is caused by a direct upregulation in LECs although some contribution of immune cells infiltrating infected lungs cannot be excluded." (PMID 35688908, 2022). "In order to clarify this issue, we searched GEO datasets for information about TACSTD2 expression after infection in specific cell types." (PMID 35688908, 2022). "Next, to analyze TACSTD2 expression in response to lung damage, we searched the Expression Atlas database for differential expression in lungs after infection or injury." (PMID 35688908, 2022). "Single cell and subpopulation based transcriptomic data revealed that the major source of TACSTD2 transcript are lung epithelial cells and their progenitors and that TACSTD2 is induced directly in lung epithelial cells following infection." (PMID 35688908, 2022). "To further confirm the effect of infection on TACSTD2 upregulation in lung cells, we searched for datasets examining TACSTD2 expression in LECs in vitro." (PMID 35688908, 2022). "Eleven differential expression datasets analyzed the levels of Tacstd2 early after infection (1–7 days), and all of them showed a significant upregulation of Tacstd2 in infected mouse lungs." (PMID 35688908, 2022). "Overall, overexpression of TACSTD2 is an early event in the lungs challenged with various infection agents." (PMID 35688908, 2022). "We found that lung levels of TACSTD2 consistently increase as an early reaction to infection with various (mainly viral) respiratory pathogens." (PMID 35688908, 2022). "Thorough analysis of Tacstd2 knockout mice upon infections with various pathogens is therefore needed to help clarify the exact role of the Trop2 protein and its signaling in lung tissue response to infections." (PMID 35688908, 2022). "After infection with the influenza A virus, Tacstd2 levels were elevated on the fourth day by approximately 20%." (PMID 35688908, 2022). "TACSTD2 silencing specifically inhibited HCV-Luc infection at all the time points examined, with even greater efficiency than mAb AR4A." (PMID 29538454, 2018). "Additionally, in most datasets, Tacstd2 overexpression peaks early and decreases over time, suggesting it is an early reaction to infection." (PMID 35688908, 2022). "The data also show that the level of Tacstd2 upregulation depend on infection dose." (PMID 35688908, 2022). "Interestingly, after infection with influenza virus, Tacstd2 expression was increased in club cells and slightly in AECs and eosinophils, but decreased in neutrophils." (PMID 35688908, 2022). "To test the hypothesis that upregulation of TACSTD2/Trop2 is a physiological reaction to lung tissue damage by infection or injury, we first verified that TACSTD2 is expressed in healthy lungs indeed." (PMID 35688908, 2022). "Datasets containing information about the dynamics of this process showed that in the case of SARS coronavirus MA15, the levels of Tacstd2 peaked two days post-infection and then started to decrease, indicating that the upregulation of Tacstd2 is an early reaction to infection." (PMID 35688908, 2022). "In this study, we use available expression datasets to test the hypothesis that the upregulation of TACSTD2 in the lungs is a physiological reaction to infection or injury, which both trigger an acute immune response." (PMID 35688908, 2022). "However, the early increase of TACSTD2 expression after infection suggests that innate immunity response may be involved." (PMID 35688908, 2022). "Interestingly, in this case Tacstd2 was also upregulated late post-infection (21 and 49 days)." (PMID 35688908, 2022).
infection (continued). "Analysis of this dataset not only confirmed that Tacstd2 levels were highest two days after SARS coronavirus infection regardless of the infection dose but also showed that a higher dose of the virus induced higher upregulation of Tacstd2." (PMID 35688908, 2022). "Silencing of TACSTD2 dramatically reduced infection by all the 8 chimeric HCV tested, regardless of their genotype, compared to the levels observed in siControl-treated cells." (PMID 29538454, 2018). "We derived Calu-3 TACSTD2 KO cells using CRISPR/Cas9 approach and analyzed their growth and epithelial barrier integrity, two processes that may be relevant for LECs response to infection." (PMID 35688908, 2022). "To study whether TACSTD2 affects infection by different HCV genotypes and subgenotypes, we tested the effect of TACSTD2 gene silencing on infection by a series of luciferase-expressing chimeric viruses representing all HCV genotypes and two subgenotypes, namely, 1a, 1b, 2b, 3a, 4a, 5a, 6a, and 7a." (PMID 29538454, 2018).
TACSTD2 also shares sentences with these, for which no sentence is quoted: non-small cell lung carcinoma (25 papers); cholangiocarcinoma (8); gallbladder cancer (8); gastrointestinal tumors (6); glioblastoma (6); lung squamous cell carcinoma (6); papillary thyroid carcinoma (6); rectal cancer (6); adenoma (5); prostate tumors (5); carcinosarcoma (4); nasopharyngeal carcinoma (4); neuroendocrine carcinoma (4); neuroendocrine tumor (4); oral cancer (4); renal cell carcinoma (4); thyroid tumor (4); breast NECs (3); chronic obstructive pulmonary disease (3); epithelial neoplasm (3); esophageal cancer (3); follicular thyroid carcinoma (3); gastric tumor (3); laryngeal carcinoma (3); leukemia (3); lymphoma (3); metastatic prostate carcinoma (3); osteosarcoma (3); ovarian tumors (3); thyroid (3).
A further 143 diseases each share a sentence with TACSTD2 in 2 papers or fewer.